CXCL12 (C-X-C motif chemokine ligand 12)
Diseases named in the same sentence as CXCL12 in open-access papers (continued):
Sharing a sentence is not in itself a finding about the gene and the disease.
tumor (continued). "Transdifferentiation of GBM tumor-derived endothelial cells has been documented by multiple groups and CXCL12 has been reported to promote in vitro tube formation and VEGF production of endothelial cells." (PMID 23555768, 2013). "Other chemokine receptors implicated in Treg trafficking to tumor sites include CXCR4, which drives Treg cells toward tumor site via interactions with CXCL12 that is produced within the tumor microenvironment, as well as CCR8 and CCR10 (86, –88)." (PMID 23874336, 2013). "The results of the present study indicate that CXCL12 overexpression itself, in different tumor models, can recruit more macrophages." (PMID 22314082, 2012). "We have directly evaluated the role of increased CXCL12 expression in in vivo tumor cell invasion, where the tumor microenvironment and paracrine loops with supporting stromal cells can influence tumor cell behavior." (PMID 22314082, 2012). "Collectively, these data indicate that CXCL12 induces the spatial/temporal association of an mDia2 and DIP complex, therein driving DIP-dependent blebbing and amoeboid transitions in motile tumor cells in both 2D and 3D matrices." (PMID 23024796, 2012). "During adhesion to C I, FN or LN for 30 or 60 min, tumour cells were treated with CXCL12 at concentrations of 25, 50 and 100 ng/ml or remained untreated." (PMID 22253872, 2012). "In solid tumors, different stromal cells express CXCL12 and/or its receptors creating paracrine interactions that promote tumor progression." (PMID 22399057, 2012). "Alternatively, CXCL12 stimulates the production of metalloproteases, which are important in local tumour invasion." (PMID 22415233, 2012). "CXCR4, together with its ligand CXCL12, is involved in tumor angiogenesis, directional metastasis, as well as resistance to chemotherapy and endocrine treatments for cancer therapy." (PMID 23071744, 2012). "CXCR4 interacts with CXCL12 to promote tumor cell proliferation, induce the expression of MMP2, and increase invasion and metastasis." (PMID 22537906, 2012). "In particular, tumor endothelial cells expressed higher levels of CXCL12 when compared to normal tissues." (PMID 22916293, 2012). "To elucidate the underlying association between CXCL12/CXCR4 expression and clinicopathological features, we assessed MVD and MLVD in tumor tissues." (PMID 23181100, 2012). "As far as cancer growth is concerned, CXCL12 may induce mitotic signals, favor metastatic evolution and contribute to the development of a microenvironment dominated by M2-polarized, anti-inflammatory, tumor-associated macrophages that support tumor cell survival." (PMID 22529914, 2012). "CXCL12 has multiple roles in tumour pathogenesis by promoting tumour growth, enhancing tumour angiogenesis, suppressing tumour immunity and participating in tumour metastasis via expression of CXCR4." (PMID 22415233, 2012). "Whereas CXCR4 was predominantly expressed by tumor cells, CXCL12 was observed in both tumor and stromal areas." (PMID 23249693, 2012). "This suggests that the CXCL12 expressed by the Neu-YB tumor cells was necessary for EGF induced in vivo invasion." (PMID 22314082, 2012). "CXCL12 can also promote TNFα expression, which can activate nuclear factor κB (NF-κB) and act back on tumour cells to induce cell surface CXRC4 expression." (PMID 22415233, 2012). "The requirement of specific, integrin-mediated adhesive contacts for sufficient CXCL12 stimulated GTPase activation in our study appears to promote increased chemotactic tumour cell motility in various metastatic target organs." (PMID 22253872, 2012). "Within 48 hours of the initiation of AMD3100 treatment, tumor cells exhibited decreased proliferation and increased apoptosis indicating that AMD3100 disrupted a critical direct effect of CXCL12 on tumor growth." (PMID 22427929, 2012).
tumor (continued). "The X-tile program (Yale University, CT, USA) was used to determine cut-points to divide the samples into low/negative, moderate and high groups using a H-score of 0–3 (low; 39%), 3–90 (moderate; 41%) and 90–300 (high; 20%) for expression of CXCL12 in tumours." (PMID 22415233, 2012). "To confirm that CXCL12 secretion by tumor cells can result in an increase in macrophage density and tumor cell in vivo invasion, we overexpressed CXCL12 in MTLn3 cells." (PMID 22314082, 2012). "Expression of CXCL12 by tumor cells results in increased macrophage and microvessel density and in vivo invasiveness." (PMID 22314082, 2012). "Our data clearly show anti-tumorigenic properties for the CXCR7 receptor in NB, as CXCR7 was able to affect in vitro migration-promoting effect mediated by the CXCR4/CXCL12 axis, and to delay orthotopic tumor take of CXCR4-positive NB cells." (PMID 22916293, 2012). "The X-tile program was also used to divide the cohort into two groups: low/high groups of H-score 0–10 (low; 55%) and 10–300 (high; 45%) for CXCL12 tumour expression." (PMID 22415233, 2012). "High expression of CXCL12 was seen in only 20% of the tumours, suggesting a role for anti-CXCL12/CXCR4 therapy in the management of these patients." (PMID 22415233, 2012). "Whereas CXCR4 was solely expressed by tumor cells, CXCL12 was observed in both tumor and stromal areas." (PMID 23249693, 2012). "In this study, we examined the role of increased production of CXCL12 in tumor cell invasion and malignancy." (PMID 22314082, 2012). "Several groups found that CXCR4 and its ligand CXCL12 can promote tumour cell migration and invasion." (PMID 22253872, 2012). "TAMs derive from circulating monocytes that are selectively attracted within the tumor microenvironment by locally produced chemotactic factors, such as CXCL12." (PMID 22485156, 2012). "We performed an in vitro chemotaxis assay with the chemokine ligands for CCR8 and CXCR4 (CCL1 and CXCL12) and observed these chemokines induced more efficient chemotaxis of tumor-infiltrating FoxP3+ T cells compared to their counterparts in lymph nodes." (PMID 22292042, 2012). "Chemokines such as CXCL1 and CXCL8 are able to enhance tumor cell proliferation; CXCL5 and CXCL12 attract neutrophils and MDSC, while CXCL12 promotes the migration of tumor cells that express the cognate receptor CXCR4." (PMID 22927846, 2012). "We then directly tested the role of CXCL12 expression in tumor cells by overexpressing this ligand in MTLn3 cells." (PMID 22314082, 2012). "Multiple preclinical studies have converged on the finding that anti-CXCL12 agents can significantly delay primary tumor growth and metastasis when treatment is started at or close to the time of tumor implantation." (PMID 22399057, 2012). "In non-neoplastic tissues, Treg are recruited by chemokines such as CXCL12 secreted by bone marrow, lymph node and inflammatory cells, a mechanism that is replicated in tumours through chemokine secretion by neoplastic cells." (PMID 21521526, 2011). "It has been suggested that CXCL12 promotes tumor invasion by inducing MMP9, which degrades extracellular matrix components." (PMID 22074556, 2011). "Our results are well in line with recent findings demonstrating a role of CXCL12 in promoting cell migration and tumor growth of CRC metastasis in vivo in a murine model." (PMID 21349176, 2011). "We have also shown that CXCL12 regulates tumor angiogenesis and that this is critical for tumor growth." (PMID 21750716, 2011). "We have shown, for example, that the α-CXC chemokine Stromal cell-Derived Factor-1 SDF-1/CXCL12 contributes to the immunosuppressive network within the tumor microenvironment, notably by orchestrating the recruitment of pre-DC2s." (PMID 21750716, 2011). "Here we report that CXCR4 overexpression increases the chemotactic and invasive behavior of MTLn3 cells, in vitro and in vivo, to CXCL12, as well as their motile behavior within the primary tumor." (PMID 22152016, 2011).
tumor (continued). "CXCR7 and CXCR4 expressed on tumor cells significantly induced proliferation and migration in the presence of CXCL12." (PMID 22180778, 2011). "CXCL12 immunoreactivity was detected in epithelium-derived proliferating tumor cells from benign tumors." (PMID 21410972, 2011). "CXCL12 was barely detectable in the stroma, and tumor epithelial cells are thus probably the principal source of CXCL12 in EOC." (PMID 21410972, 2011). "It has been heavily documented that CXCL12 is expressed in the bone microenvironment and creates migration and invasion paths for the tumor cells with CXCR4 expression." (PMID 22074556, 2011). "The CXCR4/CXCL12 receptor axis has been shown to play an important role in metastasis of CXCR4-expressing tumor cells to organs and tissues that produce high amounts of CXCL12 such as the liver, bone, lymph nodes, lungs, and brain." (PMID 21915267, 2011). "While tumour CXCL12 expression correlated with tumour Treg recruitment, this did not appear to account for the increased number of Treg observed in basal-like cancers." (PMID 21521526, 2011). "We show that CXCR4 overexpression increases chemotactic and invasive behavior, both in vitro and in vivo, in response to a CXCL12 gradient, as well as enhances the motile behavior of tumor cells within the primary tumor and their ability to intravasate." (PMID 22152016, 2011). "In vivo, CXCR7 increased primary tumor growth while it impaired invasion to CXCL12, intravasation and spontaneous lung metastasis formation." (PMID 22152016, 2011). "It is known that CXCR7, a second CXCL12 receptor, regulates TEM of CXCR4+CXCR7+ tumor cells towards a CXCL12 source." (PMID 21672222, 2011). "The authors' explanation is that when CXCL12 is produced by the tumor, the autocrine function of CXCL12 renders the tumor insensitive to its effects and cancels any metastatic potential." (PMID 22295222, 2011). "CXCR-4 is an alpha-chemokine receptor specific for CXCL12 (also called stromal-derived-factor-1 or SDF-1), a molecule endowed with potent chemotactic activity for lymphocytes and tumor cells." (PMID 22074556, 2011). "High Treg infiltration correlated with tumour CXCL12 positivity (OR 1.89, 95% CI 1.22 to 2.94, P = 0.004) and basal phenotype (OR 3.14, 95% CI 1.08 to 9.17, P = 0.004) in univariate and multivariate analyses." (PMID 21521526, 2011). "We recently showed that, although it does not directly mediate cell migration, CXCR7 can regulate TEM of CXCR4+CXCR7+ tumor cells towards CXCL12, an effect that can be blocked by CXCR7-specific antagonists and the second CXCR7 chemokine ligand, CXCL11." (PMID 21672222, 2011). "CXCR4/CXCL12 axis has been shown to enhance tumor growth by modulating tumor stroma through activation of cancer-associated fibroblasts and recruitment of CXCR4-positive endothelial precursor cells, thereby enhancing angiogenesis." (PMID 21915267, 2011). "Since the CXCL12-CXCR4 axis plays a prominent role in tumourigenesis, promoting angiogenesis and migration of tumour cells to metastatic sites, we selected CXCL12 and its receptor CXCR4 for further analyses." (PMID 20386750, 2010). "Here, the immunohistochemical detection of CXCL12 in tumour cells correlated only with distant metastases and tumour grade but not with nodal spread." (PMID 20386750, 2010). "Early high-level CXCL12 expression at the tumor site induces an anti-tumor response that depends on CD8+ T cells." (PMID 20849618, 2010). "The anti-tumor effects of CXCL12 and anti-metastatic effects of CXCL12(P2G) are therefore unlikely to be a result of reduced angiogenesis." (PMID 20849618, 2010). "CXCL12 stimulates proliferation, dissociation, migration, and invasion in a wide variety of tumor cells, including breast cancer cells, pancreatic cancer cells and HCC cells." (PMID 20380740, 2010).
tumor (continued). "In all of the patient biopsies, CD68-positive tumour-associated macrophages presented a mixed CXCL10 (M1)/CD163 (M2) pattern, expressed CXCR4, GM-CSF and HB-EGF, and some stained positive for CXCL12." (PMID 20946648, 2010). "Another significant finding of this work was that CXCL12 expression prevented the accumulation of MDSC in the spleens of tumor-bearing mice." (PMID 20849618, 2010). "Taken together, these data suggest that CXCL12 is able to induce different anti-tumor responses depending on the tumor type." (PMID 20849618, 2010). "CXCL12 has chemotactic activity towards cancer and immune cells; in both cell types, it induces cytokines that retain pro-tumour activity and modulate the stromal component, contributing to a tumour-permissive microenvironment." (PMID 20946648, 2010). "CXCL12 and its receptors are not only involved in processes specific to metastasis; many of their functions promote primary tumor growth." (PMID 20849618, 2010). "In contrast, wild-type CXCL12 blocked both metastasis and primary tumor growth in a manner that was dependent on the induction of an anti-tumor immune response." (PMID 20849618, 2010). "CXCL12 expression results in enhanced cell-mediated cytotoxicity towards tumor cells, increased accumulation of CD11c+ cells in the TDLN and reduced accumulation of MDSC in the spleen." (PMID 20849618, 2010). "All tumour samples showed a distinct CXCL12 positivity of the vascular endothelial cells, which served as an internal positive control." (PMID 20386750, 2010). "The regulation of CXCR4 surface expression by 5T4 molecules is a novel means to control responses to the chemokine CXCL12 for example during embryogenesis but can also be selected to advantage the spread of a 5T4 positive tumor from its primary site." (PMID 20376365, 2010). "Studies with knockdown cells revealed a key role for Bim in the survivability of metastatic tumor cells expressing CXCL12 in an in vivo orthotopic xenograft model." (PMID 20877573, 2010). "It is a known tumor suppressor, and downstream phosphorylation target of Akt, which is known to be activated by CXCL12 in CLL cells." (PMID 20661426, 2010). "More importantly, CXCL12 plays a crucial role in the process of invasion and metastasis of tumor cells." (PMID 20380740, 2010). "In support of this contention, we were able to show that concomitant expression of CXCL12 in tumour cells and CXCR4 in tumour microvessels correlated with local tumour growth and UICC-tumour stage." (PMID 20386750, 2010). "In support of this finding, the anti-tumor effect of CXCL12 was reduced in pfp-/- mice and in TRAIL-/- mice, suggesting that the CD8+ T cells exert their effects via the death receptor pathway as well as the granule exocytosis pathway." (PMID 20849618, 2010). "In the last years, several molecules able to target CXCR4 or CXCL12 have been developed to interfere with tumor growth, including pharmacological inhibitors, antagonists, and specific antibodies." (PMID 20049170, 2010). "The chemokine CXCL12 also exerts a direct effect on tumor cell proliferation and survival in a high variety of tumors." (PMID 20049170, 2010). "CXCL12 binds to the widely expressed CXCR4 and regulates key aspects of development, stem cell motility and tumour metastasis to tissues with high levels of CXCL12." (PMID 20376365, 2010). "In contrast, CXCL12, another relevant member of this group, promotes tumor neoangiogenesis under specific conditions, thus being regarded as one of the most powerful promalignancy factors." (PMID 20049170, 2010). "It has been demonstrated previously that that co-implantation of tumor cells with fibroblasts expressing CXCL12 enhances tumor growth." (PMID 20849618, 2010). "The statistical analyses showed a significant correlation between the expression of CXCL12 in tumour cells and distant metastases (p = 0.043) as well as tumour grade (p = 0.0064)." (PMID 20386750, 2010).
tumor (continued). "CXCR4-expressing tumor cells preferentially metastasize to tissues that highly express CXCL12, including the lung, liver, LN, and bone marrow." (PMID 20502531, 2010). "Wild-type CXCL12 similarly inhibited both spontaneous and experimental metastasis, but in contrast to CXCL12(P2G), CXCL12 concomitantly inhibited primary tumor growth." (PMID 20849618, 2010). "As CXCL12 is known to direct homing in diverse tissues and play a role in tumor metastases, it is likely that miR-886-3p expression is likely to be of significance in the regulation of both normal and disease tissue." (PMID 21179442, 2010). "While expression of CXCL12(P2G) significantly inhibited metastasis, expression of wild-type CXCL12 potently inhibited both metastasis and primary tumor growth." (PMID 20849618, 2010). "In our model, it is possible that induction of CD8+ T cell activity and IFN-γ production by tumor-derived CXCL12 drives differentiation of MDSC into mature macrophages, abrogating their immunosuppressive effects." (PMID 20849618, 2010). "on the other hand, CXCR4 is a membrane-bound G-protein-coupled receptor which, together with its ligand CXCL12, mediates inflammatory and tumor cell migration." (PMID 20181250, 2010). "When expressing both, CXCL12 in tumour cells and CXCR4 in tumour microvessels, these tumours also were highly significantly associated with higher T- and UICC-stages." (PMID 20386750, 2010). "The importance of the CXCR4/CXCL12 pathway in tumor development was further demonstrated by neutralizing the interaction between CXCL12 and CXCR4." (PMID 19340288, 2009). "CXCL12 expression was detected in tumor cells and Schwann cells around the tumor by immunohistochemical staining, and some weak staining was found occasionally in mesenchymal cells." (PMID 18983683, 2008). "Both the control group and the CXCL12-treated group had more nerves number near the tumor tissue than it found in the AMD3100-treated group." (PMID 18983683, 2008). "Of the three groups, the CXCL12-treated group had the highest average number of nerves around tumor." (PMID 18983683, 2008). "In vivo, the number of nerves around the tumor tissue in the group treated with CXCL12 was significantly higher than that found in the control group (P < 0.05)." (PMID 18983683, 2008). "The average number of nerves near the tumor was statistically higher than the average number of nerves far from the tumor in both the CXCL12-treated group and the control group (F = 9.49, P < 0.05)." (PMID 18983683, 2008). "CXCL12 can induce tumor cell secretion of MMP-9 that then degrades the blood vessel basal membrane, remodels vessels and stimulates growth of new vessels." (PMID 18983683, 2008). "SDF-1α (CXCL12) is described as a very potent constitutive chemokine for the localization of lymphocytes, homing of stem cells to bone marrow and tumor cells." (PMID 19055814, 2008). "It is therefore most probable that dp12 is affecting factors other than CXCL12 in mediating its effects on tumour growth." (PMID 17726466, 2007). "We have shown that interfering with the CXCR4/CXCL12 axis using TN14003 in vitro will effectively inhibit tumor cell migration." (PMID 18001467, 2007). "The specific involvement of the CXCR4/CXCL12 axis in cell proliferation, and organ-specific metastasis has been partially addressed and remains controversial in some tumour systems, including NB." (PMID 17925864, 2007). "The natural ligand of CXCR4, the stromal cell-derived factor (SDF-1 or CXCL12), is highly expressed in lung, liver, and lymph nodes, the preferred organs for metastasis of several tumours." (PMID 17245339, 2007). "High levels of CXCL12 were detected in the mouse adrenal gland (the primary tumour site), and in the liver suggesting a paracrine effect of host-derived CXCL12 on NB growth." (PMID 17925864, 2007).